TNF (tumor necrosis factor)
Diseases named in the same sentence as TNF in open-access papers (continued):
Sharing a sentence is not in itself a finding about the gene and the disease.
Alzheimer disease (continued). "Some KEGG enrichment results were associated with Alzheimer's disease, such as IL-17 signaling pathway (hsa04657), TNF signaling pathway (hsa04668) and the MAPK signaling pathway (hsa04010)." (PMID 36566207, 2022). "We also compared barrier disruption in response to TNF-α and conditioned medium (CM) from hiPSC-derived neurons harboring the Alzheimer’s disease (AD)-causing Swedish mutation (APPSwe/+)." (PMID 35123529, 2022). "It has been shown that high level of TNF is associated with the progression of a variety of neurological disorders, including Alzheimer's disease, as well as Parkinson's disease." (PMID 34877406, 2021). "The study found that in patients with mild cognitive frailty and mild to moderate Alzheimer's disease, the pro-inflammatory factor TNF-α was associated with an increased risk of physical frailty." (PMID 35069415, 2021). "The TNF gene encodes the pro-inflammatory cytokine TNF, also known as TNF-alpha, which plays a major role in multiple diseases and conditions, including neurodegenerative diseases such as PD and Alzheimer’s disease." (PMID 34943986, 2021). "Alzheimer’s disease patients with raised serum levels of pro-inflammatory cytokines IL-1β and TNF-α are indeed at increased risk of subsequent cognitive decline." (PMID 33723589, 2021). "In another study, high levels of circulating TNFα were observed in patients with Alzheimer’s disease experiencing unexplained weight loss." (PMID 32297262, 2020). "Our findings indicate the possible roles of apoE and TNF‐α in the pathogenesis of APOE‐ε4‐associated Alzheimer's disease." (PMID 32426945, 2020). "Microglia activation releases inflammatory cytokines, including tumor necrosis factor (TNF)-α and interleukin (IL)-1β, which initiate neurodegeneration to cause the progression of Alzheimer’s disease." (PMID 32326255, 2020). "The inflammatory score composited of blood IL-10 and other cytokines including TNF-α, IL-23, and IL-1β was negatively associated with lower FA in patients with Alzheimer’s disease." (PMID 30792621, 2019). "Intriguingly, increased peripheral TNF and other pro-inflammatory cytokine levels have been found in Alzheimer's disease, and peripheral inflammation has been linked to exacerbation of brain pathogenesis and neurodegeneration, affecting cholinergic neurons." (PMID 31024522, 2019). "Inhibition of soluble TNFα signaling in a mouse model of Alzheimer’s disease prevented Aβ-associated neuropathology." (PMID 30941000, 2019). "The opposite effect occurs in rodent models of Alzheimer’s disease, where disproportionate death of noradrenergic neurons causes increased expression of TNFα and iNOS, which can be reduced with norepinephrine administration." (PMID 31138227, 2019). "Entrance of pro-inflammatory cytokines; tumor necrosis factor-alpha (TNF-α), interleukin-6 (IL-6) has been shown to be associated with the progression of Parkinson’s disease, Alzheimer’s disease, and schizophrenia." (PMID 29937710, 2018). "In Alzheimer's disease (AD), not only is there abnormal production of TNF-α, but TNF-α has also been linked to the pathological neuromodulation of the disease." (PMID 29487525, 2018). "Consistent with this, elevated systemic TNF-α is associated with more rapid cognitive decline over 6 months in Alzheimer’s disease patients." (PMID 27633985, 2017). "Elevated levels of the cytokine tumor necrosis factor-α (TNFα) have been associated with neurodegenerative diseases such as Alzheimer's disease (AD) where increased levels of TNFα has been found in brains and cerebrospinal fluid of AD patients." (PMID 28947966, 2017). "Pro-inflammatory cytokines TNFα and IL-6 are key mediators of inflammatory responses associated with various neurological disorders including Parkinson’s disease, Alzheimer’s disease, and amyotrophic lateral sclerosis." (PMID 29228978, 2017).
Alzheimer disease (continued). "Although TNF-α has been implicated in several brain disorders, such as Alzheimer’s disease, it has yet to be explored as a specific neurotherapeutic target in ASD." (PMID 29137272, 2017). "It was reported that the increase in TNFα is associated with the pathogenesis of Alzheimer disease (AD)." (PMID 26576191, 2015). "Some inflammatory mediators associated with periodontal disease, e.g. C Reactive Protein (CRP), Interleukin 6 (IL 6), Interleukin 1(IL 1β), and TNF-α have been suggested to increase the risk of cognitive decline and/or Alzheimer’s disease." (PMID 25516763, 2014). "Elevated levels of TNF-α have been associated with various neurodegenerative diseases such as Alzheimer's disease and Parkinson's disease." (PMID 25093162, 2014). "In particular, increased tumor necrosis factor (TNF) signaling is implicated in the pathology of both Parkinson's disease (PD) and Alzheimer's disease (AD)." (PMID 24824433, 2014). "The pathogenesis of Alzheimer's disease (AD) involves upregulation of several inflammatory cytokines like TNF-α and loss of cholinergic neurons." (PMID 25140322, 2014). "Inheritance of the TNF-α (−863) C allele has been associated with elevated risk of developing Alzheimer disease." (PMID 22509108, 2012). "A C/A polymorphism at position −863 of the TNF-α promoter region has been reported to be associated with Alzheimer disease." (PMID 22509108, 2012). "Elevated levels of TNF-α have been documented in several neurodegenerative disorders including Alzheimer's disease, Parkinson's disease and HIV-associated dementia." (PMID 22277195, 2012). "Inheritance of the TNF-α (−863) C allele has been associated with an elevated risk of Alzheimer disease." (PMID 22509108, 2012). "Mutations in TNF affect susceptibility to cerebral malaria, septic shock, and Alzheimer’s disease." (PMID 40139908, 2025). "While our findings align with literature focusing on middle and later life, we observed notable distinctions, including the lack of association with a significant genetic risk factor and TNF-alpha, which has shown inconsistent links to Alzheimer’s Disease in previous research." (PMID 40242320, 2025). "High TNF‐α levels are linked to disease progression and symptom severity in neuroinflammatory conditions such as Parkinson's disease (PD), multiple sclerosis (MS), neuro‐Behçet's disease, and Alzheimer's disease (AD)." (PMID 39935210, 2025). "Microglia cells activation and release of pro-inflammatory cytokines such as TNF-α and IL-1β, which can cause neuro-inflammation by forming amyloid-beta plaque and might trigger pathogenesis in Alzheimer's disease." (PMID 37113148, 2023). "It is also hypothesized that the chronic inflammation observed in Alzheimer’s disease is associated, among other things, with increased production of cytokines of the tumor necrosis factor (TNF) family." (PMID 35054920, 2022). "Aberrant TNFα signaling has been implicated in numerous pathological conditions including cancer, rheumatoid arthritis, psoriasis, multiple sclerosis, as well as immune, inflammatory, and neurodegenerative diseases like Alzheimer’s disease (AD)." (PMID 35897073, 2022). "Single studies have reported that carriers of the A allele of the TNF-α 308 G/A gene were variably associated with increased risk of Alzheimer’s disease and that carriage the higher IL-6 producing allele of IL-6 (174 G/C) may confer increased risk." (PMID 29686666, 2018). "Considering each of these factors separately, this does not seem to match previous findings, as prior studies have shown positive associations between for instance Alzheimer’s disease and increased levels of several cytokines, and between aging and increased levels of IL-6 and TNF-α." (PMID 30261848, 2018).
Alzheimer disease (continued). "Neuroinflammation is a hallmark of Alzheimer's disease and TNFα as the main inducer of neuroinflammation has neurodegenerative but also pro-regenerative properties, however, the dose-dependent molecular changes on signaling pathway level are not fully understood." (PMID 28947966, 2017). "As TNF has been implicated as playing an important role in conditions like delirium and Alzheimer’s disease, individuals showing a prolonged elevation of TNF in the CNS may be at risk of developing such complications." (PMID 23095517, 2012). "Furthermore, inhibition of TNFα in the context of other neuroinflammatory disorders such as MS and Alzheimer's disease (AD) has very recently been shown to be associated with progressive multifocal leukoencephalopathy (PML) and demyelination." (PMID 21494611, 2011). "Accordingly, Calogero Caruso (University of Palermo, Italy) reviewed the reports indicating an association between the risk of Alzheimer Disease (AD) and polymorphisms of genes encoding inflammatory mediators, such as IL-1β, IL-6, IL-10 and TNF-α, as well as the possible involvement of Zn." (PMID 17883856, 2007). "In the incidence of Alzheimer’s disease, the release of this inflammatory mediator can cause neuronal cell death, according to a study by Janelsinset al., which stated that the inflammatory mediators TNF-α and IL-1β appears to be directly proportional to Alzheimer’s disease severity." (PMID 34367622, 2020). "When serum TNF and CSF α-synuclein levels are considered together, ≥ 82% sensitivity and 83% specificity were achieved in both HC and PD groups across all time points; CSF tau and Aβ demonstrate comparable sensitivity (but less specificity) as diagnostic tools for Alzheimer’s disease." (PMID 28821274, 2017). "Given the potential similarities in cellular events leading to neurodegeneration between Alzheimer disease and glaucoma, we hypothesized that TNF-α (−863) polymorphism may be a genetic factor predisposing affected individuals to glaucoma due to its effect on TNF-α protein expression." (PMID 22509108, 2012). "The rapid response to perispinal etanercept may provide an important clue to the pathophysiologic mechanisms underlying not only Alzheimer's disease, but also other brain disorders involving excess TNF-alpha and cognitive dysfunction, including frontotemporal dementia, and traumatic brain injury." (PMID 18184433, 2008). "The need to better understand the role of tumor necrosis factor-alpha (TNF-α) in Alzheimer's disease (AD) and its relationship with brain atrophy and cognitive decline is highly relevant." (PMID 41960503, 2026). "The advancement to knowledge in this study is the identification of a significant correlation between elevated TNF-α levels and hippocampal atrophy in Alzheimer's disease, supporting TNF-α as a potential biomarker for disease progression." (PMID 41960503, 2026). "This also provides a possible explanation for how sporadic Alzheimer’s disease develops and it would be informative to expose IC neurons to TNF-α for longer times in future work to see how the pathology develops." (PMID 39749010, 2025). "Several studies have described elevated TNF-α levels in patients with Alzheimer’s disease (see metanalyses)." (PMID 39155063, 2025). "For instance, it can influence signaling of TNF-α and other cytokines, and it has been found upregulated in models of Alzheimer’s disease and other conditions with innate immune activation." (PMID 41226356, 2025). "In neurodegenerative diseases such as Alzheimer’s disease (AD), activated microglia initiate neuroinflammation by releasing cytokines (IL-1β, IL-6, and TNF-α), leading to neuronal damage, Aβ plaque accumulation, and tau hyperphosphorylation." (PMID 40242775, 2025). "In Alzheimer’s disease, TNF-α has been linked to amyloid-beta (Aβ) plaque accumulation and synaptic dysfunction, whereas in Parkinson’s disease, TNF-α-mediated microglial activation leads to dopaminergic neuron degeneration." (PMID 40430212, 2025).
Alzheimer disease (continued). "Sarcosine has been shown to be neuroprotective in experimental Alzheimer’s disease model; neurofibrillary tangles in brain were significantly attenuated, along with higher levels of antioxidants and lower expression levels of TNF-α." (PMID 40865967, 2025). "The other pathways that are affected include VEGFR2 signaling, and Alzheimer’s disease, alongside the critically important B cell receptor signaling and TNF alpha signaling." (PMID 40453371, 2025). "Tumor necrosis factor-α as an inflammatory marker showed a significant elevation in the rats’ group of Alzheimer’s disease in comparison with all studied groups." (PMID 39850118, 2025). "AVE0991 treatment in the APP/PS1 double-transgenic mouse model of Alzheimer’s disease suppressed astrocyte-mediated inflammation by downregulating the expression profile of IL-1β, IL-6, and TNF-α in the brain cortex." (PMID 40565247, 2025). "Recent studies utilizing animal models have shown the capacities of anti-TNFα and anti-IL-1β in attenuating neurological deficits in Alzheimer’s disease, Parkinson’s disease, and ischemic stroke." (PMID 40338234, 2025). "Both IL-6 and TNF-α are neurotoxic and are elevated in other neurodegenerative conditions including Alzheimer’s disease." (PMID 41009444, 2025). "Previous studies have uncovered that MMP-2 and TNF-α have important roles in the progression of other diseases, such as Alzheimer’s disease and Parkinson’s disease." (PMID 38429778, 2024). "Other important inflammatory mediators believed to play a role in chronic neurodegenerative diseases as Alzheimer’s disease are TNFα and nitric oxide released by microglia." (PMID 38572181, 2024). "Others have reported that AD-16 was able to reduce IL-1β expression induced by LPS in vivo, restore IL-4 and IL-6 levels in a mouse model of Alzheimer’s disease, and reduce IL-1β and TNF-α levels in the brain of ischemic mice." (PMID 39736920, 2024). "Work with experimental animal models has shown that TNF neutralization is an effective therapeutic in heart disease and neurodegenerative diseases like Alzheimer's disease." (PMID 38459711, 2024). "The main signaling pathways involving these DEPs included the Ras signaling pathway, linoleic acid metabolism, alpha-linolenic acid metabolism in Alzheimer's disease, actin cytoskeleton regulation, and the TNF signaling pathway." (PMID 39635211, 2024). "Even though AS patients had a higher prevalence of Alzheimer's disease compared to the general population, among the patients with AS, those treated with TNF inhibitors had lower rates of Alzheimer's disease." (PMID 38571822, 2024). "Studies have shown that it can inhibit the production of TNF-α, a particularly beneficial process in the context of Alzheimer’s Disease (AD)." (PMID 39457411, 2024). "In this regard, serum concentrations of some inflammatory cytokines, such as IL-1β, TNF-α, and IL-6, increase with advancing age and are highly expressed in patients with Alzheimer's disease (AD) or depression." (PMID 38300639, 2024). "More recently, it was reported that treatment with Tan IIA reduced the expression of proinflammatory cytokines such as NF-κB, TNF-α, IL-6, and IL-1β in Alzheimer's disease model." (PMID 39687171, 2024). "The role of tumor necrosis factor-α (TNF-α) in Alzheimer’s disease (AD) has recently become a topic of debate." (PMID 38397814, 2024). "Examples include the Alzheimer disease–associated amyloid precursor protein (APP), tumor necrosis factor (TNF) and its receptors, Notch, and the interleukin-6 (IL-6) receptor." (PMID 38897568, 2024). "EA reduces the expression of IL-1β, IL-6, and TNF-α in the hippocampus of mice with Alzheimer’s disease and acute myocardial ischemia, exerting an anti-inflammatory effect." (PMID 38629101, 2024). "In clinical setting, it has been demonstrated that peripheral TNF-α elevation enhances brain pro-inflammatory cytokine expression and Alzheimer’s disease patients exhibit high level of serum TNF-α concentrations." (PMID 39135795, 2024).
Alzheimer disease (continued). "Biologic TNF-α inhibitors (bTNFIs) can block cerebral TNF-α in Alzheimer’s disease (AD) if these macromolecules can cross the blood–brain barrier (BBB)." (PMID 38500108, 2024). "TNF-α variants and TNF-α itself have also been linked to varying degrees with an augmented risk of Alzheimer’s disease." (PMID 38002398, 2023). "The TNF‐α level usually elevates in neuroinflammatory injuries, including Alzheimer's disease, encephalopathy, and ST." (PMID 36655100, 2023). "Tumor necrosis factor-alpha (TNF-α) is a master cytokine involved in a variety of inflammatory and neurological diseases, including Alzheimer’s disease (AD)." (PMID 37355890, 2023). "Chronic inflammation is a known cause for neuronal loss, and many pro-inflammatory cytokines, such as tumor necrosis factor alpha (TNF-α) and interleukin-6 (IL-6), are found to be elevated in Alzheimer’s dementia (AD)." (PMID 37371414, 2023). "In cerebral hypoperfusion and Alzheimer's disease models, activated glia was shown to release proinflammatory factors such as IL-1β, IL-6, TNF-α, COX-2, and iNOS, promoting further neuronal degeneration in the hippocampus." (PMID 37064799, 2023). "It was also reported that levels of peripheral cytokines, such as IL-1β, TNF-α, IL-6, and C reactive protein, were significantly higher in elderly with Alzheimer’s disease." (PMID 37623235, 2023). "Compared with a heathy control group, patients with Alzheimer's disease (AD) showed significantly increased peripheral levels of IL-6 and TNF-α." (PMID 37962457, 2023). "Microglia-derived proinflammatory cytokine TNF-α has been confirmed to contribute to neuronal cell cycle events in the pathogenesis of Alzheimer’s disease." (PMID 37264405, 2023). "TNF plays a role in neurodegenerative disorders like Alzheimer's disease and neuropsychiatric disorders." (PMID 38115011, 2023). "In neurodegenerative conditions like Alzheimer’s disease (AD), chronic inflammation plays a pivotal role in the disruption of the blood–brain barrier, primarily driven by signaling molecules such as TNFα and IL-1β." (PMID 38002034, 2023). "Studies of Alzheimer’s disease show inflammatory cytokines such as TNF-α, IL-1, IL-6, and IL-8 are released from the host cells that have been infected with Porphyromonas." (PMID 37007475, 2023). "SOD1 has not been reported in AAA, but when treated with hydroxyl ethanol, it inhibits Ang II-induced Alzheimer’s disease, decreases the expressing of NF-κB, P65, TNF-α, and IL-1β, and increases the conveying of SOD1, MMP9, and GCLC in mice." (PMID 37737183, 2023). "In a study, rutin showed a reduced production of TNF-α and IL-1β production, which are very common pro-inflammatory factors in the microglia in Alzheimer’s disease." (PMID 36145202, 2022). "BBB disruption is caused by the secretion of pro-inflammatory mediators, such as IL-1α, IL-1β, IL-6, and TNF-α, due to an increase in microglia and astrocytes in Alzheimer’s disease." (PMID 35453602, 2022). "TNF-α plays a crucial role in various autoimmune and neurological disorders, including Alzheimer’s disease (AD)." (PMID 36037389, 2022). "A possible mechanism involves the ability of Tnk1 to induce TNFα-dependent apoptosis by preventing activation of NF-κB, as TNFα is known to be important in driving the progression of Alzheimer’s disease." (PMID 36334623, 2022). "In different clinical research, some proinflammatory factors (such as IL-6, IL-1β, and TNF-α) were reported to be overexpressed in patients with Alzheimer's disease and elderly people with mild cognitive impairment." (PMID 36147643, 2022). "High levels of proinflammatory cytokines such as interleukin (IL)-1β, IL-6, and tumor necrosis factor-alpha (TNF-α) have been detected in the brains of patients with Alzheimer’s disease." (PMID 35887634, 2022). "It was also indicated that the expressions of pro-inflammatory factors, such as interleukin-1β (IL-1β) and tumor necrosis factor alpha (TNF-α), were increased in cancer and Alzheimer’s disease." (PMID 35203561, 2022).